MIF (macrophage migration inhibitory factor)
Diseases named in the same sentence as MIF in open-access papers (continued):
Sharing a sentence is not in itself a finding about the gene and the disease.
periodontitis (10 papers, 2018 to 2025). An acute or chronic inflammatory process that affects the tissues that surround and support the teeth. "In conclusion, when we contemplate these findings, we can consider MIF as a potential early diagnostic biomarker for gingivitis and progression to periodontitis among the tested three chemokines namely MAF, MCF and MIF." (PMID 36747174, 2023). "Macrophage migration inhibitory factor (MIF) has been noted to play a role in both periodontitis and cancer." (PMID 35047982, 2020). "On that account, it has been described in a periodontitis model in mice that MIF promote the activation of transcription factors that activate osteoclastogenesis." (PMID 30868074, 2019). "MIF expression was higher in the periodontal tissue of chronic periodontitis patients than in that of healthy patients." (PMID 29482504, 2018). "Furthermore, they discovered that fibroblasts regulate NETs formation during periodontitis through the macrophage migration inhibitory factor (MIF)-CD74/CXCR4 axis." (PMID 40486514, 2025). "Increased levels of macrophage migration inhibitory factor were described in chronic periodontitis." (PMID 36979679, 2023). "Furthermore, MIF has been shown to be increased in both serum and gingival tissue of patients with periodontitis." (PMID 38275363, 2023). "Finally, macrophage migration inhibitory factor (MIF), another important effector cytokine of the innate immune system, has been also associated with the disease severity in chronic periodontitis." (PMID 34064456, 2021). "Thus, MIF biomarker might have an essential function in the pathology and development of chronic periodontitis." (PMID 36747174, 2023). "Examine the effects of periodontitis and RA on the serum and saliva concentrations of MCP‐1, MIF, and fractalkine." (PMID 39811802, 2025). "Some studies have identified MIF overexpression in GCF from subjects with gingivitis, in gingival tissue from subjects with CP, in serum and tissue of mice with induced periodontitis." (PMID 30868074, 2019).
renal fibrosis (10 papers, 2016 to 2025). A final common manifestation of a wide variety of chronic kidney diseases characterized by glomerulosclerosis and tubulointerstitial fibrosis. "TGF-β stimulates M2a macrophages by activating the ATF6/TGF-β/SMAD3 pathway, leading to the activation of macrophage migration inhibitory factor (MIF) that induces the transition of macrophages to myofibroblasts in renal fibrosis." (PMID 39867890, 2024). "On the one hand, macrophage migration inhibitory factor exerts a protective effect in anti-oxidation and macrophage migration inhibitory factor-2 promotes cell proliferation and ameliorates renal fibrosis." (PMID 36117692, 2022). "As CD74 is a major receptor of MIF, we hypothesize that targeting MIF should also decrease renal fibrosis in ADPKD kidneys." (PMID 38534333, 2024). "Knockout of MIF also decreases renal fibrosis in Pkd1 mutant mouse kidneys, and knockdown of CD74 blocks MIF induced the expression of fibrotic markers, supporting a novel mechanism that MIF is through CD74 to regulate the transcription of fibrotic markers followed by renal fibrosis." (PMID 38534333, 2024). "Additionally, MIF limited tubular cell cycle arrest, another pathological process contributing to renal fibrosis." (PMID 35096904, 2021). "Therefore, as a critical macrophage regulator, MIF is considered to be an important inflammatory factor involved in the synthesis and accumulation of matrix and renal fibrosis." (PMID 27313397, 2016). "However, whether targeting MIF also decreases renal fibrosis in Pkd1 mutant kidneys remains unknown." (PMID 38534333, 2024). "It seems that MIF may negatively contribute to an inflammatory reaction and renal fibrosis." (PMID 27313397, 2016). "To investigate how MIF regulates renal fibrosis through CD74, we treated rat renal fibroblast NRK-49F cells with either MIF or ISO-1." (PMID 38534333, 2024). "Various inflammatory factors, including TNFα, MIF, and TGF-β, have been reported to promote renal fibrosis in ADPKD, in which TGF-β has been identified as the most important regulator of renal fibrosis." (PMID 39456148, 2024). "The effect was inhibited by MIF antagonist ISO-1, suggesting the role of MIF as a potential upstream mediator of EMT that results in matrix deposition and subsequent renal fibrosis." (PMID 30787934, 2019). "Our study suggests that MIF triggers the activation of TGF-β-Smad signaling in a CD74 dependent manner via CD74 mediated the transcription regulation of TGF-β and fibrotic marker genes to regulate renal fibrosis in ADPKD kidneys." (PMID 38534333, 2024). "Surprisingly however, using several ways to manipulate MIF in a comprehensive set of models of interstitial injury and renal fibrosis, MIF was found to significantly limit rather than promote both renal fibrosis and inflammation." (PMID 35096904, 2021).
amyotrophic lateral sclerosis (9 papers, 2018 to 2025). Amyotrophic lateral sclerosis (ALS) is a neurodegenerative disease characterized by progressive muscular paralysis reflecting degeneration of motor neurons in the primary motor cortex, corticospinal tracts, brainstem and spinal cord. "MIF and PVALB are associated with amyotrophic lateral sclerosis, a neurodegenerative disease targeting motor neurons." (PMID 34763096, 2022). "Moreover, the protective effect of MIF has been reported in amyotrophic lateral sclerosis where elevated MIF levels inhibited the accumulation of misfolded SOD1." (PMID 38178143, 2024). "However, elevated MIF seems to play a detrimental role in neurodegenerative pathologies, among them Epilepsy, traumatic brain injury (TBI), Parkinson’s disease, and Amyotrophic Lateral Sclerosis (ALS)." (PMID 34662363, 2021).
atopic dermatitis (9 papers, 2014 to 2025). "Regression analysis for age- and sex-adjusted log [MIF] levels with the MIF polymorphisms in patients with atopic dermatitis." (PMID 27598332, 2016). "Regression analysis for age- and sex-adjusted log [total IgE] with MIF polymorphisms among patients with atopic dermatitis." (PMID 27598332, 2016). "Single‐cell RNA sequencing revealed that MIF signaling drives inflammatory fibroblastmyeloid cell crosstalk in atopic dermatitis." (PMID 41059955, 2025). "A recent study observed that MIF amounts were increased in the allergen-induced skin tissue of atopic dermatitis murine models, and the elevated MIF levels promoted the secretion of IL-4 and IL-5, and eosinophil recruitment in the skin." (PMID 34305594, 2021). "Atopic individuals with allergic asthma, allergic rhinitis, and atopic dermatitis frequently express high levels of MIF." (PMID 33804792, 2021). "Plasma MIF and log [total IgE] levels are significantly elevated in atopic dermatitis (AD) patients." (PMID 27598332, 2016). "High levels of the MIF expression have been found in a variety of inflammatory conditions, including atopic dermatitis, and inflammatory skin lesions." (PMID 24586879, 2014). "Impact of the MIF –173G/C and –794 [CATT]5–8 polymorphisms [OR (95% CI)] on atopic dermatitis." (PMID 27598332, 2016). "Additionally, in a mouse model of induced atopic dermatitis, EGCG lowered IgE serum levels and decreased mRNA expression of TNF-α, MIF (macrophage migration inhibitory factor), IFN-γ, IL-2, and IL-12 in skin lesions." (PMID 38248322, 2023).
Crohn disease (9 papers, 2008 to 2025). A gastrointestinal disorder characterized by chronic inflammation involving all layers of the intestinal wall, noncaseating granulomas affecting the intestinal wall and regional lymph nodes, and transmural fibrosis. "Furthermore, increased MIF concentrations were found in patients with Crohn's disease." (PMID 25821795, 2015).
diabetic nephropathy (9 papers, 2010 to 2025). "Macrophages are a major inflammatory cell in diabetic nephropathy (DN), which may be associated with the upregulation of MIF." (PMID 35563296, 2022). "Inhibition of MIF in a diabetic nephropathy model ameliorated blood glucose and albuminuria and in a model of adult polycystic kidney disease cyst growth was delayed." (PMID 26858715, 2016). "MIF has been reported to increase and participate in the pathogenesis of diabetic nephropathy." (PMID 23319831, 2012). "It is hypothesized that increased macrophage migration inhibitory factor(MIF) expression may contribute to diabetic nephropathy (DN) pathogenesis.The aim of the present study was to investigate the renal effects of MIFinhibition in a diabetic experimental model." (PMID 30720852, 2019). "Thus, MIF may play a pathological role in diabetic nephropathy." (PMID 35563296, 2022). "CD74 is a multifunctional protein and a receptor for Macrophage Migration Inhibitory Factor (MIF) and MIF-2 / D-dopachrome tautomerase (DDT) cytokines, upregulated in diabetic kidney disease." (PMID 29924850, 2018). "The serum MIF concentration is elevated in T2DM individuals 19 and MIF and CD74 are two overexpressed genes in human diabetic nephropathy." (PMID 25661015, 2015). "Whether inhibition of MIF or oxMIF may offer promising therapies in clinical conditions, such as AKI, CKD, diabetic nephropathy, inflammatory kidney diseases, and ADPKD, needs to be elaborated in future interventional studies." (PMID 26858715, 2016).
Hypertension (9 papers, 2012 to 2024). The presence of chronic increased pressure in the systemic arterial system. "Arterial hypertension on the other hand was independently associated with higher MIF-levels." (PMID 22693633, 2012). "Arterial hypertension was the predominant comorbidity in 85% of patients with increasing MIF concentrations (vs. decreasing MIF: 39%; p = 0.015)." (PMID 33671433, 2021). "Only one pre-existing condition, namely hypertension, was strongly associated with the Non-Responder, respectively the high-level MIF group and higher mortality for ARDS patients with SARS-CoV-2 infection." (PMID 33671433, 2021). "Serum MIF was increased in SSc patients with low forced vital capacity (FVC) and was also associated with the use of angiotensin II receptor blockers and beta blockers in SSc, confirmed after adjusting for the presence of systemic hypertension and low FVC." (PMID 30546906, 2018). "Patients with high MIF levels were in general older, had more often arterial hypertension, hyperlipidemia, were more often treated with ASA, clopidogrel, statins and AT1-inhibitors and had a more preserved left-ventricular function compared to patients with low MIF-levels (≤1.96 ng/mL)." (PMID 22693633, 2012). "Serum MIF was significantly increased in SSc patients receiving angiotensin II receptor blockers or beta blockers, while not in those with a diagnosis of systemic hypertension, a finding confirmed in multivariable analysis after adjusting for the presence of systemic hypertension and low FVC." (PMID 30546906, 2018). "We also observed that increased serum MIF concentrations were associated with the use of the antihypertensive drug classes angiotensin II receptor blockers and beta blockers in SSc, and this association was independent of the presence of systemic hypertension." (PMID 30546906, 2018).
injury (9 papers, 2012 to 2025). Damage inflicted on the body as the direct or indirect result of an external force, with or without disruption of structural continuity. "Furthermore, the increases in the pro-inflammatory cytokine, IL-18, and macrophage migration inhibitory factor (MIF) reported here have also previously been shown to increase their spinal cord expression following nerve injury, and have been implicated in contributing to sensory abnormalities." (PMID 25905723, 2015). "In the CYP (cyclophosphamide)‐induced bladder injury mouse model, the interaction types and signals (MK, MIF, GDF and CXCL) of fibroblasts and myofibroblasts significantly increased compared with the normal group." (PMID 36824020, 2023). "It has been reported that MIF knockout mice showed a strong increase in fibrosis in a mouse model of chronic liver injury." (PMID 30404232, 2018). "Hypothermia downregulated the expression of migration inhibitory factor (MIF) in a rat model of traumatic brain injury." (PMID 22776061, 2012). "In a septic kidney injury model, MIF inhibits mitophagy by disrupting the PINK1-Parkin interaction." (PMID 41357167, 2025). "Moreover, high levels of serum MIF were also found in CLP-induced acute lung injury in rats." (PMID 38313162, 2023). "The combination of MIF and CD74 could also inhibit cell apoptosis, promote cell proliferation and alveolar epithelial cell repair, and at the same time play a role in reducing lung inflammation and acute lung injury." (PMID 37853311, 2023).
lymph node metastasis (9 papers, 2014 to 2025). "In NPC tissue, the high-expression of MIF and IL-8 was significantly associated with increased intratumoral microvessel density and microvessels or lymph node metastasis in NPC patients." (PMID 27788497, 2017). "In another study it was reported that, overexpressed MIF in gastric adenocarcinoma increased lymph node metastasis." (PMID 41159021, 2025). "In total, there were eighteen L‐R pairs decreased in NPC patients with lymph node metastasis, and the communication probability of five pairs including MIF‐(CD74 + CXCR4), MIF‐(CD74 + CD44), LGALS9‐CD45, IL16‐CD4 and CCL19‐CCR7 were increased in NPC_LNM." (PMID 39392128, 2024). "In lung squamous cell carcinoma, tumor MIF expression correlates with lymph node metastasis and worse disease-free survival, and in mesothelioma, CD74 tumor enrichment independently predicts improved survival." (PMID 38732068, 2024). "In patients with nasopharyngeal carcinoma, increased MIF tumor expression is a strong prognostic factor for lymph node metastasis and worse survival." (PMID 38732068, 2024). "A recent study also confirmed that MIF could be used as one of the predictors of lymph node metastasis and prognosis in LUAD." (PMID 36358600, 2022). "In turn, nuclear MIF was correlated with lymph node metastasis (p = 0.003)." (PMID 34157052, 2021). "MIF plays a role in angiogenesis, lymph node metastasis and distant metastasis." (PMID 30742638, 2019).
oral squamous cell carcinoma (9 papers, 2014 to 2025). "The present study aimed to investigate MIF as a potential marker for disease control or recurrence, and to assess the association between serum and salivary MIF and the clinicopathological characteristics of patients with oral squamous cell carcinoma (OSCC)." (PMID 25289107, 2014). "Melatonin inhibits the development of oral squamous cell carcinoma by interrupting the MIF/NLRP3/IL-1β signaling pathway promoted by macrophages." (PMID 40756978, 2025). "Macrophage migration inhibitory factor (MIF) was suggested to play a predominant role in M2 macrophage polarisation, and MIF depletion spontaneously reverts TAMs to an M1-like polarisation, as found in oral squamous cell carcinoma." (PMID 38473281, 2024). "In addition, it has been reported that MIF may be a novel prognostic marker for human oral squamous cell carcinoma." (PMID 36465348, 2022).
osteoarthritis (9 papers, 2011 to 2025). A noninflammatory degenerative joint disease occurring chiefly in older persons, characterized by degeneration of the articular cartilage, hypertrophy of bone at the margins and changes in the synovial membrane. "A substantial body of experimental and observational evidence supports the effect of lowering MIF levels in reducing osteoarthrosis severity through limiting tissue damage related to its pro-inflammatory effects." (PMID 38378567, 2024). "We undertook this study to investigate the role of MIF in OA by examining MIF genotype, mRNA expression, and protein levels in the Newfoundland Osteoarthritis Study." (PMID 33610191, 2021). "Knockout of MIF in elderly mice reduced the severity of osteoarthritis, and MIF-specific inhibitor treatment exhibited effective anti-inflammatory effects in vitro and in vivo." (PMID 33601337, 2021). "Elevated levels of MIF expression were observed in synovial tissues and synovial fluids from RA patients compared to osteoarthritis (OA) patients or healthy volunteers." (PMID 34535196, 2021). "Synovial fluid MIF concentration in RA patients was significantly higher than in osteoarthritis (OA) patients." (PMID 21401926, 2011). "However, the results also indicated that there were no preventive effects on destabilization of the medial meniscus-induced osteoarthritis in young mice treated with MIF neutralizing antibody." (PMID 40169556, 2025). "The latest studies revealed that MIF plays a protective role in osteoarthritis." (PMID 34621738, 2021). "Therefore, we undertook this study to investigate the potential role of MIF in OA by systematically examining MIF genotypes, mRNA and protein expressions in a well-established OA cohort—the Newfoundland Osteoarthritis Study (NFOAS)." (PMID 33610191, 2021). "More intense staining of MIF and RANKL was observed in synovium from patients with RA compared with synovium from patients with osteoarthritis (OA)." (PMID 21401926, 2011).
steatosis (9 papers, 2013 to 2025). Increased lipid within the cytoplasm of cells. "MIF exhibits a protective effect against steatosis, resulting in a decreased quantity of macrophages." (PMID 36221095, 2022). "The action of MIF signals interacting with the HLA class II histocompatibility antigen (CD74) receptor mitigates the steatosis of liver cells." (PMID 36147562, 2022). "Hepatocyte-derived Mif expression was required for ethanol-induced liver injury, steatosis, and cellular stress, directly connecting hepatocyte-derived MIF as necessary to drive ethanol-induced liver injury and inflammation." (PMID 33945507, 2021). "Protection from steatosis by MIF involved inhibition of hepatic fatty degeneration and was mediated through the CD74/AMPK axis in hepatocytes and a shift in hepatic macrophage polarization." (PMID 33525493, 2021). "We described a putative mechanism by which MIF exerts its steatosis-preventing effect by demonstrating AMPK-dependent lipid oxidation in HepG2 cells." (PMID 23823021, 2013). "Previous data indicated that MIF has a hepatoprotective effect in steatosis and fibrosis by promoting the CD74/AMPK pathway in hepatocytes and Mif–/– mice on a non-Western-type HFD showed enhanced lipid accumulation in the liver, which was associated with upregulated Srebp-1 and Fasn levels." (PMID 40055309, 2025). "Although we did not observe differences in lipid storage in liver or skeletal muscle, MIF-mediated changes may be important later in the disease, such as the development of steatosis." (PMID 38973609, 2024). "Immunohistological investigation of MIF expression in liver biopsies from the NAFLD patients in this study showed that MIF staining was increased in both hepatocytes and MNCs in NASH patients compared to those with only steatosis." (PMID 26124760, 2015).